CCND1 (cyclin D1)
Diseases named in the same sentence as CCND1 in open-access papers (continued):
Sharing a sentence is not in itself a finding about the gene and the disease.
biliary tract cancer (1 paper, 2010).
blood disease (1 paper, 2018). A disease that occurs in the blood. "The possibility that RBM11 modulates the splicing of CCND1, and an array of oncogenic genes in EWS, is consistent with known roles for related RNA binding proteins (RBM), including RBM10, RBM15 and RBM25, which alter gene splicing to promote various forms of blood disease and cancer." (PMID 30093970, 2018).
bone metastasis (1 paper, 2018). Transfer of a neoplasm from its primary site to bones. "Expression of cyclin D1 was significantly associated with distant metastatic relapse, latent bone metastasis, ER expression, PR expression, and MMP9 expression." (PMID 29416639, 2018).
bone sarcoma (1 paper, 2015). A sarcoma that arises from the bone. "Stimulation of the Wnt/β-catenin by Wnt3a markedly triggered c-Myc expression in bone sarcoma cells, whereas downregulation of β-catenin/TCF signaling resulted in reduction of c-Myc and cyclin D1 levels and decreased cell proliferation." (PMID 25999350, 2015).
breast disease (1 paper, 2013). "Elevated expression of CCND1 was commonly associated with a more aggressive breast disease phenotype and an adverse patient outcome." (PMID 23547709, 2013).
breast papillary carcinoma (1 paper, 2025). A breast carcinoma characterized by the formation of irregular, finger-like projections of fibrous stroma covered with neoplastic epithelial cells. "11q13.3 gains were also found in 12% of breast papillary carcinomas, encompassing CCND1, and copy number gain of CCND1was also identified in our study." (PMID 40994809, 2025).
carcinoids (1 paper, 2015). "Based on our results, carcinoids seem to use the signaling cascade via upregulation of CDK4/6 and CCND1 expression to control RB1 phosphorylation." (PMID 26008974, 2015). "In contrast, CCND1 (p = 0.0012) and CDK6 (p < 0.0001) showed elevated expression in carcinoids compared to carcinomas." (PMID 26008974, 2015). "Carcinoids have increased CDK4/6 and CCND1 expression controlling RB1 phosphorylation via this signaling cascade." (PMID 26008974, 2015).
cardiac arrest (1 paper, 2021). Cessation of breathing and/or cardiac function. "In particular, in ischemic human brain, cyclin D1 is upregulated in nuclei and cytoplasm of scattered neurons within infarcted tissue after cardiac arrest." (PMID 34439951, 2021).
cardiomyopathy (1 paper, 2023). A disease of the heart muscle or myocardium proper. "Thus, our study is the first evidence of CCND1’s upregulation in IDCM adult patients at an early stage, and CCND1 might be a potential newfound gene for cardiomyopathy." (PMID 37372424, 2023).
Cerebellar medulloblastoma (1 paper, 2015). "In Ptch+/− mice, known to develop spontaneous cerebellar medulloblastomas, loss of cyclin D1 (Ptch+/−; Ccnd1−/−) significantly reduces the incidence of tumors." (PMID 26061748, 2015).
childhood cancer (1 paper, 2023). "CDK2 is associated with CCND1, which regulates cell proliferation, the cell cycle, and DNA damage repair in childhood cancer through the regulation of Rb." (PMID 37444539, 2023).
chronic gastritis (1 paper, 2025). Inflammation of the stomach that is chronic in nature.
chronic lymphocytic thyroiditis (1 paper, 2023). "Cyclin D1 protein expression was positively correlated with tumor size (P < 0.05) and lymph node metastasis (P < 0.05), but was not significantly correlated with patient sex, age, number of tumor nests, histological subtype, the presence or absence of chronic lymphocytic thyroiditis or TNM stage." (PMID 37951919, 2023).
clear cell chondrosarcoma (1 paper, 2020). A rare, usually low grade chondrosarcoma characterized by the presence of tumor cells with clear cytoplasm. "Increased Cyclin D1 function leading to vascularized clear cell tumors may be a common molecular feature of VHL-associated tumors and clear cell chondrosarcoma, which could be useful for therapeutic purposes in the future." (PMID 31673890, 2020).
congenital mesoblastic nephroma (1 paper, 2019). A low grade childhood congenital malignant neoplasm arising from the kidney. "All 4 cases of congenital mesoblastic nephroma (CMN) in our study showed markedly intense (3+) focal to diffuse staining for Cyclin D1." (PMID 30736802, 2019).
congestive heart failure (1 paper, 2023). Failure of the heart to pump a sufficient amount of blood to meet the needs of the body tissues, resulting in tissue congestion and edema. "Furthermore, DisGeNET data show that two genes, including STAT1 and CCND1, have not been associated with IDCM, but STAT1 is related to congestive heart failure." (PMID 37372424, 2023).
cortical dysplasia (1 paper, 2016). "The relative expression of LIN28A (3.8–156.9-fold; p = 0.009), LIN28B (4.1–76.9-fold; p = 0.012) and CCND1 (5.7–126.0-fold; p = 0.009) were higher in AT/RT tissues, compared with cortical dysplasia tissues." (PMID 27095948, 2016).
craniopharyngioma (1 paper, 2022). A benign, partly cystic, epithelial tumor of the sellar region, presumably derived from Rathke pouch epithelium. "Abnormal cell cycle regulation is an important event of tumorigenesis; we evaluate the cell-cycle-associated markers including cyclin D1, P16, and Ki-67 expression in craniopharyngioma by immunohistochemistry staining." (PMID 35707464, 2022). "Cyclin D1 expression was significantly related to the histological type of craniopharyngioma (p = 0.038)." (PMID 35707464, 2022). "However, expressions of TRKA, cyclin D1, and P16 and their relationship with BRAF V600E mutation in craniopharyngioma have not been reported." (PMID 35707464, 2022).
cystadenocarcinoma (1 paper, 2004). A malignant cystic epithelial neoplasm arising from the glandular epithelium. "Increases in the cyclin D1 LIs were observed in the serous cystadenocarcinomas." (PMID 15083189, 2004).
dementia (1 paper, 2019). Loss of intellectual abilities interfering with an individual's social and occupational functions. "DS dementia strongly correlates with overexpression of miR-155 on chromosome 21 with concomitant reduction of multiple CNS-functional targets, including BACH1, CoREST1, Cyclin D1, BCL6, BCL10, BIM, and SAPK4." (PMID 31824553, 2019). "Recent evidence suggests that DS dementia strongly correlates with overexpression of miR-155 on chromosome 21 with concomitant reduction of multiple CNS-functional targets, including BACH1, CoREST1, Cyclin D1, BCL6, BCL10, BIM, and SAPK4." (PMID 31824553, 2019).
dental caries (1 paper, 2025). The decay of a tooth, in which it becomes softened, discolored, and/or porous. "Furthermore, CCND1 also demonstrated a significant association with the progression of dental caries (odds ratio = 1.15564, 95% CI 1.05554-1.26523, p = 0.0018), while SLC6A4, CASP3, NR3C1, and ANXA1 were linked to diseases of the pulp and periapical tissues." (PMID 41023518, 2025).
dermatitis (1 paper, 2023). An inflammatory process affecting the skin. "Other cell signaling pathways including cell cycle and NF-kB pathway (CCND1), autophagy (ATG16L2, ATG10), wnt/β-catenin (APC, GSK3β) and angiogenesis (EDN1) regulating genes were associated with RT related acute mucositis and dermatitis." (PMID 37954025, 2023).
dermatofibromas (1 paper, 2016). "Of note, studies have shown that some dermatofibromas resemble superficial BCCs, and the β-catenin-induced dermatofibromas in our study expressed typical BCC markers such as K17 and cyclin D1." (PMID 26771241, 2016).
disc degeneration (1 paper, 2016). "In the Wnt/β-catenin pathway, β-catenin, c-myc and cyclin D1 mRNA expression decreased in OVX rats (p < 0.05), indicating that Wnt/β-catenin pathway down-regulation accompanied disc degeneration caused by ovariectomy." (PMID 27279629, 2016). "β-catenin, c-myc and cyclin D1 mRNA expression in the OVX+E2 and OVX+PTH groups were higher than those in the OVX group, indicating that oestrogen and PTH could increase the Wnt/β-catenin pathway expression at the same time as when they relieve disc degeneration." (PMID 27279629, 2016).
dwarfism (1 paper, 2021).
Ehrlich tumor (1 paper, 2023). "Ehrlich tumor tissue significantly stimulated oncogenes expression of NF-κB, p38 MAPK, and cyclin D1 compared with normal control." (PMID 36905557, 2023).
embryonal tumor (1 paper, 2020). "Our results using a cyclin D1-dependent hematologic malignancy, a MYC-dependent embryonal tumor, and a PI3K-dependent solid tumor demonstrate that SRX3177 is efficacious and non-toxic in vitro to normal epithelial cells." (PMID 32793389, 2020). "To characterize the effect of SRX3177 in detail, we measured cytotoxic activity of this inhibitor in a cyclin D1-dependent hematologic malignancy (mantle cell lymphoma), a MYC-dependent embryonal tumor (neuroblastoma), and a PI3K-dependent solid tumor (hepatocellular carcinoma)." (PMID 32793389, 2020).
endocrine neoplasia (1 paper, 2020). "Two particular genes have been implicated in the pathogenesis of parathyroid tumorigenesis: the cyclin D1/PRAD1 (parathyroid adenomatosis 1) oncogene and the MEN1 (multiple endocrine neoplasia type 1) tumor-suppressor gene." (PMID 32570711, 2020).
endometrial endometrioid adenocarcinoma (1 paper, 2018). A primary endometrial adenocarcinoma composed of neoplastic cells that form complex glandular patterns associated with budding and branching of the neoplastic glands. "Currently, there are no FDA-approved or NCCN-compendium listed treatments specifically for patients with CCND1-mutant uterine endometrioid carcinoma." (PMID 29969496, 2018).
endometrioid tumor (1 paper, 2013). A benign, borderline, or malignant epithelial tumor of the female reproductive system characterized by the presence of glands and/or cysts lined by neoplastic cells that resemble endometrial cells. "Cyclin D1 is also an important mediator of estrogen-dependent endometrial cell proliferation and is over expressed in endometrioid tumors." (PMID 23843797, 2013).
fibrolamellar carcinoma (1 paper, 2012). "We detected cyclin D1-immunoreactive cell populations also in fibrolamellar carcinoma, usually considered as a slowly proliferating type of cancer." (PMID 22292081, 2012).
food allergies (1 paper, 2024).
fungal infection (1 paper, 2012). "The induction of p52- and p65-heterodimers by fungal infection could therefore explain in part the down-regulation of cyclin-D1, -E and Skp2." (PMID 22396644, 2012).
gastroesophageal reflux disease (1 paper, 2024). A chronic disorder characterized by reflux of the gastric and/or duodenal contents into the distal esophagus. "For instance, gastroesophageal reflux disease (GERD) has a known heritability estimate of roughly 31% based upon twin and family studies, with known risk genes including FOXF1, MHC, and CCND1." (PMID 38527901, 2024).
gastrointestinal carcinomas (1 paper, 2017). "Perhaps this is due to similar CCND1 gene expressions in gastrointestinal carcinomas rather than tumors of other systems." (PMID 29049220, 2017).
glaucoma (1 paper, 2023). Increased pressure in the eyeball due to obstruction of the outflow of aqueous humor. "We found that Cdk1 (cyclin-dependent kinase 1) was increased in UON and MON ON crush and glaucoma tissues at three days, though cyclin D1 (Ccnd1), its downstream target was not." (PMID 37762022, 2023).
gliosarcoma (1 paper, 2022). A rare histological variant of glioblastoma (WHO grade IV) characterized by a biphasic tissue pattern with alternating areas displaying glial and mesenchymal differentiation (WHO). "Gliosarcoma had 100% expression of cyclin D1, but the mean expression percentage is 10%." (PMID 35223330, 2022).
Gliosis (1 paper, 2016). Gliosis is the focal proliferation of glial cells in the central nervous system. "Levels of p4E‐BP1, 4E‐BP1, peIF4E, eIF4E, and cyclin D1 and the Ki67 proliferative index were significantly lower in gliosis than in neoplasm in the whole group (P = 0.004 for cyclin D1, P < 0.001 for the other proteins)." (PMID 27440383, 2016).
goblet cell adenocarcinoma (1 paper, 2020). "Kanthan and colleagues published an interesting study evaluating goblet cell adenocarcinoma (GCA) and reported that their high cellular proliferation rate was a consequence of cell cycle dysregulation, in particular, with upregulation of cyclin D1 and p21, and downregulation of p16." (PMID 32466539, 2020).
Graves disease (1 paper, 2021). Graves' disease is an autoimmune disorder that leads to overactivity of the thyroid gland (hyperthyroidism).It is caused by an abnormal immune system response that causes the thyroid gland to produce too much thyroid hormones. "Previous studies in a murine model of Graves’ disease have shown that diosgenin can inhibit the proliferation of thyroid cells by inhibiting the expression of IGF-1, NF-κB, cyclin D1, and PCNA and alleviate goitre." (PMID 33737640, 2021).
hearing loss (1 paper, 2012). "The methylation of TP73, the negative expression of cyclin D1, the positive expression of B7-H1, increased expression of platelet-derived growth factor A, underexpression of PEX5L, RAD54B, and PSMAL, and overexpression of CEA are factors associated with hearing loss and VS." (PMID 22567403, 2012).
HIV-1 infection (1 paper, 2012). The type species of lentivirus and the etiologic agent of acquired immunodeficiency syndrome (AIDS). "Moreover, the perturbation of eIF4E, a critical regulator of other transcription or translation factors including Cyclin D1, and Pim-1, may also result in an inhibition of HIV-1 infection." (PMID 22808186, 2012).
hyperlipidemia (1 paper, 2022). "More importantly, AKT1, VEGFA, CCND1, ESR1 are the key targets of AM to alleviate hyperlipidemia induced by HFD." (PMID 35267929, 2022). "So far, we believe that AM may alleviate hyperlipidemia induced by HFD by downregulating the AKT1 and CCND1 protein levels and upregulating the levels of VEGFA and ESR1 protein." (PMID 35267929, 2022). "The previous bioinformatics analysis results showed that AM might alleviate hyperlipidemia by HFD through regulating the expression of four key targets (AKT1, VEGFA, CCND1 and ESR1)." (PMID 35267929, 2022). "Overall, AM alleviated acquired hyperlipidemia through regulating lipid metabolism, and AKT1, VEGFA, CCND1 and ESR1 might be the key targets." (PMID 35267929, 2022). "In conclusion, AM alleviated acquired hyperlipidemia in mice fed with HFD through regulating lipid metabolism, and AKT1, VEGFA, CCND1 and ESR1 may be the key targets." (PMID 35267929, 2022). "The results of network pharmacology and bioinformatics analysis in the current study showed that AM might alleviate acquired hyperlipidemia by downregulating the expression of AKT1 and CCND1 and upregulating the expression of VEGFA and ESR1." (PMID 35267929, 2022). "So far, we believe that AM may reduce the expression of AKT1 and CCND1 and increase the expression of VEGFA and ESR1 to alleviate hyperlipidemia induced by HFD." (PMID 35267929, 2022). "Supportably, it could be seen that AKT1 and CCND1, VEGFA and ESR1 were involved in hyperlipidemia-related diseases and several studies had uncovered the regulation of AM on these genes in different diseases." (PMID 35267929, 2022).
hyperplastic polyp (1 paper, 2021). A polyp found mainly in the stomach and colon. "As might be expected, the Ki-67 LI was positively correlated with Cyclin D1 in both tubular adenomas and hyperplastic polyps, especially the latter, where the correlation was 0.50 (p<0.0001)." (PMID 34762658, 2021).
hyperthyroidism (1 paper, 2013). Overactivity of the thyroid gland resulting in overproduction of thyroid hormone and increased metabolic rate. "For example, hyperthyroidism, mutations in the sonic hedgehog (Shh) signaling pathway, loss of cilia proteins, or loss of cyclin D1/D2, result in reduced GCP proliferation and this leads to foliation patterns that resemble an early developmental stage when the overall pattern is simpler." (PMID 23691221, 2013).
hypospadias (1 paper, 2024). Hypospadias is the displacement of the urethral meatus on the ventrum of the penis. "We utilized RT‐PCR and Western blot techniques to investigate the Wnt signaling pathway and observed a significant reduction in both mRNA and protein levels of SOX9, Wnt3a, LEF1, GSK3β, NF‐κB, TCF1, and cyclin D1 in the samples of hypospadias." (PMID 40626133, 2024).
infarction (1 paper, 2018). A localised pathological necrosis of tissue resulting from obstruction of the blood supply usually by a thrombus, an embolus, or vascular torsion. "Our recent study has demonstrated that both cardiomyocytes and fibroblasts expressed periostin and ablation of periostin suppressed post-infarction myocardial regeneration by inhibiting the PI3K/GSK3β/cyclin D1 signaling pathway, suggesting a proliferating ability of periostin." (PMID 29872491, 2018).
inflammatory breast carcinoma (1 paper, 2020). An advanced, invasive breast adenocarcinoma characterized by the presence of distinct changes in the overlying skin. "We identified cyclin D1 at the plasma membrane in inflammatory breast cancer, and cyclin D1 colocalized to the cytoplasmic membrane with PACSIN II and Paxillin (Y118) in MRC-5 cells." (PMID 32948740, 2020).
inflammatory myofibroblastic tumor (1 paper, 2019). A multinodular intermediate fibroblastic neoplasm that arises from soft tissue or viscera, in children and young adults. "By histopathological examination, the lesion was diagnosed as anaplastic lymphoma kinase-negative inflammatory myofibroblastic tumor (IMT) based on focal immunoreactivity with cyclin D1." (PMID 31223599, 2019).
insomnia (1 paper, 2022). A sleep disorder characterized by difficulty in falling asleep and/or remaining asleep. "These high-degree protein targets may be the key targets such as neurotrophic receptor tyrosine kinase 1, nuclear receptor subfamily 3 group C member 1, cyclin D1, erb-B2 receptor tyrosine kinase 2, and account for the essential therapeutic effects of CWT on insomnia." (PMID 36110515, 2022).
iron deficiency (1 paper, 2019). "As the role of iron in regulation of cyclin D1 expression is not completely understood, we investigated the molecular mechanism underlying decreased cyclin D1 mRNA and protein levels in MCL cell lines after DFO‐induced iron deficiency." (PMID 31517438, 2019).
leiomyosarcoma (1 paper, 2023). An uncommon, aggressive malignant smooth muscle neoplasm, usually occurring in post-menopausal women. "However, cyclin D1 has also been expressed in undifferentiated endometrial sarcoma and leiomyosarcoma without the YWHAE-FAM22 rearrangement." (PMID 35876683, 2023).